MTOR (mechanistic target of rapamycin kinase)
Diseases named in the same sentence as MTOR in open-access papers (continued):
Sharing a sentence is not in itself a finding about the gene and the disease.
cancer (continued). "Identifying mTOR and the PI3K/AKT/mTOR pathway as a potential therapeutic target in RIPF is attractive as it is already a pathway being exploited as a radiation sensitizer in many cancers." (PMID 29518028, 2018). "The mTOR pathway activation is reported to be involved in the autophagy inhibition in various types of cancers." (PMID 29788929, 2018). "RICTOR plays an important role in the PI3K/AKT/mTOR signaling pathway, which is one of the most commonly activated pathways in human cancer." (PMID 30139386, 2018). "In contrast to KEAP1, which we identified as novel target, mTOR has been suggested also by others based on the PI3K/mTOR pathway as the most frequently activated cascade for cancer initiation and progression." (PMID 29719593, 2018). "The PI3K/AKT/mTOR signaling network is one of the most frequently activated pathways in human cancer and is subject to complex cross-talk and feedback." (PMID 29487712, 2018). "mTOR inhibitors are also being studied, and they seem to be a good treatment option for some kinds of cancers, including gynecological ones, since their use alone or in combination with other hormonal drugs are good strategies that need further studies." (PMID 29455659, 2018). "Understanding the complex role of mTOR in regulating signal transduction is critical to developing more effective therapies to target metabolic reprogramming in cancer." (PMID 30347859, 2018). "The interaction of miR-144 and mTOR and its clinical significance have been evaluated in human cancer biology." (PMID 30305865, 2018). "The identification of DEPTOR as a direct mTOR inhibitor has led to a wave of studies investigating its role in cancer development and progression." (PMID 29330362, 2018). "The mTOR signalling pathway is frequently activated in various types of human cancer, and this activation leads to tumour progression." (PMID 29266795, 2018). "Aberrant activation of the AKT/mTOR pathway is widely observed in various malignant tumors, which accelerates proliferation, increases resistance to apoptosis and promotes invasion and metastasis." (PMID 30326933, 2018). "Current targeted approaches aim to eliminate tumor cells by disrupting the activated cancer-signaling pathway such as PI3K/AKT/mTOR signaling which is well-known to be upregulated in EC." (PMID 30380719, 2018). "In PCa, GAS5 has been shown to promote apoptosis and inhibit cell proliferation and cancer progression by targeting miR-103 and the mTOR pathway." (PMID 29416676, 2018). "Activated mTOR contributes to OS cellular transformation and poor cancer prognosis via targeting the downstream effectors such as EIF4E." (PMID 29921292, 2018). "Epigenetic modification including G9a silencing regulates mTOR/AMPK pathway in cancer, indicating autophagic cell death." (PMID 30158521, 2018). "Since mTOR signaling is activated in multiple types of cancers, targeting mTOR signaling is a therapeutic strategy to treat cancer." (PMID 29849119, 2018). "The PI3K/Akt/mTOR/p70S6K pathway is likely the most frequently activated pathway in human cancers, making it an attractive target for anti-cancer drug development." (PMID 30050147, 2018). "The tumor suppressor PTEN is well known as key negative regulator for the PI3K/Akt/mTOR pathway, and it has been proposed as powerful target for cancer treatment." (PMID 30515268, 2018). "Aberrant activation of the PI3K/Akt/mTOR pathway is often found in human cancers and promotes cell proliferation." (PMID 30363988, 2018). "The PI3K/Akt/mTOR signaling pathway is a prototypic survival pathway and is activated in many types of cancer disease." (PMID 30283336, 2018). "As PI3K-Akt-mTOR pathway is always activated in human cancers, it is believed to be the target for inactivation in order to achieve better chemotherapy." (PMID 29535821, 2018).
cancer (continued). "The AKT targeting of mTOR signaling pathway is hyper-activated or altered in many cancer types and regulates a broad range of cellular processes including survival, angiogenesis, and metastasis." (PMID 29301329, 2018). "The activated PI3K/Akt/mTOR pathway has been shown to decrease the BH3 (Bcl-2 homology domain) mimetic effectiveness in cancer cells by upregulating anti-apoptotic Bcl-2 family members, such as Mcl-1." (PMID 30110936, 2018). "As the mTOR axis is regulated by upstream PI3K/AKT signals, which are aberrantly active in several solid tumors, enhanced mTOR activity is also found in those patients, creating a promising cancer therapeutic target." (PMID 29518028, 2018). "We observed that treating infected macrophages with TNFR neutralizing antibodies decreased mTOR phosphorylation at Ser-2448, as previously reported for cancer cells; it also reduced expression of SREBF1, an mTORC1-activated gene." (PMID 30161232, 2018). "The use of mTOR inhibitors in the treatment of various types of cancer has been actively studied both preclinically and clinically." (PMID 30107094, 2018). "The rhythmic mTOR activities affect the efficacy of everolimus, a rapalog mTOR inhibitor that is clinically applied to treat cancers of the kidney, pancreas, breast, and brain." (PMID 30250482, 2018). "Because mTOR signaling plays a key role in cancer and immune cell function, it is possible that some of the anticancer effect of mTOR inhibitors is via immune modulation." (PMID 29662490, 2018). "How the IFN system regulates the autophagy pathway is largely unexplored; however, IFN treatment of cancer cells triggers autophagy via PI3K/mTOR signaling." (PMID 29381763, 2018). "FGFR3 promotes the survival of cancer cells just by stimulating the downstream PI3K/AKT/mTOR pathway." (PMID 29545752, 2018). "Targeting mTOR in cancer will promote apoptosis and nutrient deprivation, whereas inhibition of mTOR in T cells can promote the differentiation of memory T cells." (PMID 30123774, 2018). "Recent studies demonstrate the intriguing role of mTOR to achieve the feat through metabolic reprogramming in cancer." (PMID 30347859, 2018). "We know that PI3K/AKT/mTOR pathway is a prototypic survival pathway in cancers, whose activation is closely related to cellular proliferation, growth, and mobility." (PMID 29545752, 2018). "Deregulated mTOR signaling in cancer cells modulates the tumor microenvironment, thereby affecting tumor immunity and possibly promoting carcinogenesis." (PMID 29662490, 2018). "Two array panels were used here: one which profiles expression of 84 genes related to cancer drug resistance, and one which profiles expression of 84 genes related to mTOR pathway signalling." (PMID 29374181, 2018). "The PI3K pathway defined by PI3K, AKT and mammalian Target of Rapamycin (mTOR) controls most hallmarks of cancer, including proliferation, survival and motility, and contributes to cancer-promoting aspects of the tumor environment, such as angiogenesis." (PMID 29455662, 2018). "Activation of the PI3K/Akt/mTOR signaling pathway is a central event in many types of cancer and represents a promising target for new treatment strategies." (PMID 30237403, 2018). "RPS6KB2, the target gene of miR-4433a-3p, participates in cancer progression through the mTOR signalling pathway." (PMID 30381359, 2018). "Many studies have shown that the Akt/mTOR pathway plays a key role in the pathogenesis of cancer, including GBM." (PMID 30123135, 2018). "For instance, LY294002 is a strong inhibitor of PI3K and is derived from the flavonoid quercetin, which has also been described to inhibit mTOR activity in cancer cells." (PMID 30459740, 2018).
cancer (continued). "Many cancers display activation of the phosphatidylinositol 3-kinase (PI3K)/protein kinase B (AKT)/mammalian target of rapamycin (mTOR) pathway, which plays an important role in controlling the proliferation and metabolism of cancer cells." (PMID 28616837, 2018). "As PI3K/AKT is an upstream regulator of the rapamycin-sensitive mTOR complex, mTOR signaling activity is accentuated in PRL-3-positive cancer cells." (PMID 29514683, 2018). "It has been shown that the therapeutic inhibition of the PI3K/AKT/mTOR pathways leads cancer cells to upregulate RTK activity." (PMID 28513565, 2017). "Our findings not only have created a plausible three-dimension relationship among these proteins, but should also greatly help the development of new therapeutic strategies for the treatment of mTOR related diseases, in particular various cancers." (PMID 28968999, 2017). "In a sarcoma tumor model, it was reported that expression of PD-L1 on cancer cells was associated with cell-intrinsic signaling via the PI3K/Akt pathway and mTOR, leading to expression of glycolysis genes and enhanced glycolytic metabolism." (PMID 28443090, 2017). "Conversely, genetic and pharmacological inhibition of Snail function restores 4E-BP1 expression and sensitizes cancer cells to mTOR kinase inhibitors by enhancing 4E-BP1-mediated translation-repressive effect on cell proliferation and tumor growth." (PMID 29263324, 2017). "Both the cFLIP and the PI3K/AKT/mTOR pathways have been investigated intensively as targets for treatment in various types of cancers, including AML." (PMID 29254232, 2017). "The AKT/mTOR pathway is frequently abnormal in a variety of cancers, making it an attractive target for anti-cancer therapies." (PMID 29079731, 2017). "In cancer T cells, expression of CD44 has been linked to enhanced mTOR activation as the result of RasGRP1 mutations." (PMID 29180720, 2017). "Signaling through the PI3K/mTOR pathway is frequently upregulated in cancer, making this pathway a common therapeutic target for anticancer agents." (PMID 28537878, 2017). "Recent studies have revealed that inhibition of mTOR signaling using rapamycin can enhance sensitivity of cancer cells to cisplatin and doxorubicin." (PMID 28422725, 2017). "The inhibitory effects on EGFR (pEGFR –tyr1173) and AKT (pAKT Serine473) signaling, downregulates downstream pro-survival signaling (mTOR and NF-κB) in cancer cell lines." (PMID 29234489, 2017). "mTOR inhibitors have shown limited efficacy in cancers, when used in monotherapy, partly due to the reactivation of AKT signaling pathway." (PMID 29069732, 2017). "The PI3K/Akt/mTOR pathway plays a critical role in cancer progression by regulating cell growth, proliferation, and survival." (PMID 28280736, 2017). "Typical cancer-related pathways, such as Apoptosis pathway, MTOR signaling pathway, RAS signaling pathway, Phospholipase-D signaling pathway, and HIF-1 signaling pathway were returned by SPECifIC." (PMID 29657291, 2017). "One of these, paclitaxel, has been shown in cancer cell line experiments to improve in efficacy when used in combination with an MTOR-inhibitor." (PMID 28617226, 2017). "The function of csMVP is mediated through mTOR, FAK, ERK and Akt signaling pathways, which are closely associated with cancer cell survival and metastasis." (PMID 29038587, 2017). "Of relevance to this, increase in cell size has also been attributed to EMT and activation of the mTOR pathway in cancer cells." (PMID 29258566, 2017).
cancer (continued). "A novel therapeutic target of mTOR inhibitors was used to control advanced cancers and prolong the survival time of cancer patients." (PMID 29179457, 2017). "By now, several researches have demonstrated that overexpression of LAT1 can stimulate cancer growth via mTOR pathways and be closely related with poor prognosis of several cancers." (PMID 28977862, 2017). "Further investigation using other potential genomic candidates and next-generation mTOR inhibitors is warranted in patients with refractory cancer." (PMID 28330462, 2017). "Deregulation of the PI3Ks/Akt/mTOR pathway is one of the most common mechanisms responsible for development and progression of many cancer types." (PMID 28696382, 2017). "AMP-activated protein kinase (AMPK) and the mammalian target of rapamycin (mTOR) are important protein kinases in maintaining cellular energy homeostasis and glucose metabolism in cancer cells." (PMID 28969010, 2017). "Administration of the CR mimetic rapamycin (sirolimus), an immunosuppressant drug and established inhibitor of mTOR, extends lifespan and delays cancer in mice." (PMID 28539118, 2017). "First, p-mTOR positivity was higher in AC than in other types of cancers, as shown in the literature." (PMID 28831205, 2017). "Upstream and downstream targets of mTOR seem to be involved in cancer progression in low and high grade RC while in low grade and high grade CC the mTOR pathway members plays a less important role." (PMID 29254159, 2017). "Increasing evidence has supported the role of the PI3K/AKT/mTOR signaling pathway in the maintenance of CSC in several cancers." (PMID 28445151, 2017). "Our study provided new data and more evidence of Tan II A inhibited cancer cell proliferation through blocking the PI3K- Akt – mTOR - p70S6K1 signaling pathway and subsequently activation of autophagocytosis pathway in A375 cells." (PMID 28532456, 2017). "Previous study has demonstrated that the growth inhibition of cancer cells by mTOR inhibitor treatment was p-4E-BP1 dependent, which is consistent with our finding." (PMID 29290965, 2017). "The PI3K/AKT/mTOR signaling pathway has been extensively studied and demonstrated to be critical for RT resistance in various cancer types." (PMID 28978144, 2017). "In the cancer setting, the most important control over mTOR activity is via the phosphoinositide-3-kinase/Akt—protein kinase B/mTOR (PI3K/Akt/mTOR) pathway." (PMID 28192480, 2017). "The higher levels of SLC1A5 in various types of cancer cells are considered to be essential for cell proliferation and survival via the mTOR/p-70S6K1 signalling pathway." (PMID 29100325, 2017). "Mammalian Target of Rapamycin complex 2 (mTORC2) and its regulatory component Rapamycin-insensitive companion of mTOR (RICTOR) are increasingly recognized as important players in human cancer development and progression." (PMID 28445935, 2017). "In recent years, the mammalian target of rapamycin (mTOR) has aroused much interest in cancer research." (PMID 28192480, 2017). "In this review, we discuss the present and future relevance of mTOR inhibitors in cancer therapy by focusing on their effects on tumor angiogenesis." (PMID 29104248, 2017). "Deregulation of cap-dependent translation by mTOR-mediated phosphorylation of 4E-BP1 plays an important role in cancer progression." (PMID 29263324, 2017). "This compound inhibited the proliferation of cancer cells but displayed less toxicity compared to inhibitors of PI3K or mTOR." (PMID 28916818, 2017). "Surprisingly, rDNA copy number is reduced in cancer genomes with mTOR activation, providing evidence that copy number can be altered in a natural system." (PMID 28640831, 2017).
cancer (continued). "Recent studies showed that the translational landscape of mTOR signaling steers cancer initiation and metastasis and that mTORC1 senses lysosomal amino acids through an inside-out mechanism requiring V-ATPase activity." (PMID 28504970, 2017). "GSK-3 role in cancer is often dependent on GSK-3-driven mammalian target of rapamycin (mTOR), a signaling molecule crucial in cell proliferation." (PMID 29379583, 2017). "Second, our study reveals Snail as an important determinant of cancer cell sensitivity to mTOR inhibitors." (PMID 29263324, 2017). "Little is known about pharmaceutical agents targeting cFLIP in cancer cells, but some therapeutic agents have been shown to downregulate cFLIP, including histone deacetylase inhibitors, mTOR inhibitors, proteasome inhibitors, and a Cox-2 inhibitor." (PMID 29254232, 2017). "The incidence of de novo cancer was significantly lower in the mTOR inhibitor group compared to the CNI group (0.60% vs. 1.61%; p-value <0.001)." (PMID 28338305, 2017). "Evidence collected to date shows that microRNAs can regulate the mTOR signaling pathway and affect cancer cell sensitivity to chemotherapy drugs." (PMID 28422725, 2017). "The PI3K/mTOR/AKT pathway is one of the most frequently activated signaling cascades in human cancer." (PMID 27903983, 2017). "In the mTOR inhibitor group, all patients who died of cancer progression were due to advanced-stage solid organ tumors." (PMID 28160552, 2017). "A possible explanation for the synergistic action of inhibitors of the PI3K/mTOR pathways with inhibitors of glycolysis was recently found in cells derived from various cancer types." (PMID 28724379, 2017). "Metformin induces the liver kinase B1 (LKB1)-mediated activation of AMPK, which in turn blocks mTOR signaling and protein synthesis in many cancer cell lines." (PMID 28126011, 2017). "One of the molecular mechanisms underlying the anti-cancer effects of metformin is the activation of AMPK, which results in suppression of mTOR signaling." (PMID 28525374, 2017). "Whereas mTORC1 inhibition reduces the survival of normal cells in hypoxia, it supports the emergence of tumour cells that are resistant to hypoxia because, in a situation of restoration of mTOR signalling, cancer cells become sensitive to hypoxia again." (PMID 29383126, 2017). "The PI3K/mTOR signaling pathway is one of the most frequently disrupted intracellular pathways in human cancer, where it contributes significantly to tumor progression and development of resistance to chemotherapeutic drugs." (PMID 29296217, 2017). "Elevated SIRT1 expression was found in hepatocarcinoma cells when compared to non-cancerous hepatocytes, and NAMPT inhibition led to cell death via the AMPK/mTOR pathway, offering a novel strategy to prevent cancer cell growth in vivo." (PMID 28160567, 2017). "There was significant overlap; 8/14 genes involved in OGID were somatically mutated in a diverse range of cancers (NSD1, EZH2, DNMT3A, PTEN, CHD8, HIST1H1E, MTOR, PIK3CA; p = 1.7 × 10−14)." (PMID 28475857, 2017). "Accumulating evidences demonstrate that Akt/mTOR signaling pathway plays a crucial role in cancer progression." (PMID 29190940, 2017). "mTOR kinase is a major negative regulator of autophagy, and mTOR signaling is frequently dysregulated in cancer, where LKB1/AMPK signaling can act upstream of it." (PMID 28974016, 2017). "AKT regulates cell survival function and confers resistance to apoptosis by upregulating mTOR signaling axis in cancer cell types." (PMID 29234489, 2017). "The direct effects of metformin mainly occur through the induction of AMP-activated protein kinase (AMPK), consequently reducing mammalian target of rapamycin (mTOR) signaling and protein synthesis in cancer cells." (PMID 29137418, 2017).